ZNF589 (zinc finger protein 589)
Description:
May play a role in hematopoietic stem/progenitor cell differentiation. May play a role as a DNA binding-dependent transcriptional repressor.
Synonyms: SZF1
Tractability: PROTAC: ubiquitination databases record sites on it.
Gene: Protein-coding gene on chromosome 3 (48,241,100 to 48,299,253, forward strand). Ensembl gene ENSG00000164048.
Subcellular location: Nucleus
Subcellular location (Human Protein Atlas): Nucleoplasm
Pathways (Reactome):
Gene expression (Transcription): Generic Transcription Pathway
Gene Ontology:
Molecular function: DNA-binding transcription repressor activity, RNA polymerase II-specific; RNA polymerase II transcription regulatory region sequence-specific DNA binding; RNA polymerase II cis-regulatory region sequence-specific DNA binding; sequence-specific DNA binding; zinc ion binding
Biological process: negative regulation of transcription by RNA polymerase II; regulation of DNA-templated transcription
Cellular component: nucleoplasm; nucleus
Genetic constraint (gnomAD): Loss-of-function variants: 17 observed, 15.17 expected, observed/expected ratio (o/e) 1.12, 90% interval 0.76 to 1.66. The upper end of that interval is the gene's LOEUF score, 1.66, which puts it in group 6 of 6, group 1 being the genes least tolerant of losing a copy. Missense variants: 407 observed, 453.3 expected, observed/expected ratio (o/e) 0.9, 90% interval 0.83 to 0.98. Synonymous variants: 148 observed, 170.5 expected, observed/expected ratio (o/e) 0.87, 90% interval 0.76 to 1.
Homologues: Orthologues: macaque ZNF589 (96% identical), chimpanzee ZNF589 (93% identical), Drosophila melanogaster Phs (16% identical), Drosophila melanogaster CG3281 (15% identical), Drosophila melanogaster CG2712 (13% identical). Paralogues in human: ZNF133 (45% identical), ZNF343 (45% identical), ZNF875 (43% identical), PRDM9 (41% identical), ZNF169 (37% identical), ZNF337 (34% identical), ZNF10 (26% identical), ZFP90 (25% identical), ZNF425 (25% identical), ZNF550 (25% identical), ZNF778 (25% identical), ZNF614 (25% identical), and 50 more.
Diseases named in the same sentence as ZNF589 in open-access papers:
ZNF589 is named in the same sentence as 9 diseases in open-access papers, as found by Europe PMC text mining. Sharing a sentence is not in itself a finding about the gene and the disease. The quoted sentences say what the papers report.
breast carcinoma (1 paper, 2014). "Several of these genes have previously been associated with stem cell functions: MAFB and ZNF589 have been shown to be important in lineage-specific haematopoiesis, while HES4 is a down-stream target of the Notch signalling pathway which has been shown to affect breast cancer stem cell activity." (PMID 24583601, 2014).
Hypertension (1 paper, 2022). The presence of chronic increased pressure in the systemic arterial system. "ZNF589 is a member of Krüppel-associated box domain zinc-finger family of epigenetic regulators known to maintain pluripotency in HSCs,244 and adrenergic β1-receptor is an independent factor in predicting the treatment outcome for hypertension with β-blockers." (PMID 35991314, 2022).
pancreatic cancer (1 paper, 2023). "Although LIPE, MT2A, PLD4 and ZNF589 have been studied in other tumours, their relationship with tumour-associated macrophages in pancreatic cancer remains to be investigated." (PMID 37469705, 2023). "However, ABCB4, ENPP6, FGFBP2, MT2A, OXER1, PLD4 and ZNF589 were low expressed in pancreatic cancer tissues." (PMID 37469705, 2023).
ZNF589 also shares sentences with these, for which no sentence is quoted: cancer (2 papers); tumor (2); digestive system carcinoma (1); Kleefstra syndrome (1); lung carcinoma (1); viral infection (1).